RNF8 (ring finger protein 8)
Diseases named in the same sentence as RNF8 in open-access papers (continued):
Sharing a sentence is not in itself a finding about the gene and the disease.
breast carcinoma (continued). "Previous studies have suggested that the RNF8 gene could be novel tumor suppressor, but it seems that germline mutations predisposing to breast cancer in this gene do not exist or, at least, are very rare." (PMID 21774837, 2011). "For the rest of the evaluated cell lines, a possible resistant mechanism is active as described in human breast cancer, like the overexpression of TLR4 (toll-like receptor-4), overexpression of RNF8 (finger protein 8), and overexpression of HER2, among others." (PMID 40646890, 2025). "Through a literature investigation, we found that RNF8, a predicted target hub gene that was also selected in the PPI network, was recently proven to promote EMT process and therefore facilitate breast cancer metastasis." (PMID 31709182, 2019). "To explore this possibility, we first overexpressed RNF168 and two other DDR-related E3-ligases, RNF4 and RNF8, in the MCF-7 breast carcinoma cells, and studied their effects on FOXM1 expression." (PMID 27526106, 2016). "Here we report that RNF8 is overexpressed in highly metastatic breast cell lines and its overexpression can induce EMT in breast cancer cells." (PMID 27259701, 2016). "Collectively, these data suggest that RNF168 cooperates with RNF8 to mediate the ubiquitination and degradation of SUMOylated FOXM1 in breast cancer genotoxic response." (PMID 27526106, 2016). "Notably, our data also indicate that an increase in RNF8 and SNAI1 mRNA levels and a decrease in CDH1 mRNA were observed in malignant subtypes of breast cancer, i.e., TNBC patients." (PMID 34357122, 2021). "Further study firstly suggested that miR-214 could inhibit RNF8 to regulate EMT and thus suppress breast cancer." (PMID 34299149, 2021). "Combined with the results of the dual-luciferase assay showing that miR-622 could bind to RNF8 at its 3'-UTR to induce posttranscriptional silencing, we conclude that miR-622 can directly regulate RNF8 in breast cancer cells, verifying the miR-622-RNF8 axis." (PMID 31709182, 2019). "Here, we identify RNF8 as a novel factor involved in EMT and breast cancer metastasis." (PMID 27259701, 2016). "To further support our hypotheses in vitro, we chose breast cancer, in which the role of miR-622 has never been studied previously, and RNF8, one of six hub genes identified previously, as proof of the concept of our bioinformatic analysis." (PMID 31709182, 2019). "Thus, we hypothesize that miR-622 might regulate breast cancer cell EMT process and migration as a tumor suppressor gene via the downregulation of RNF8." (PMID 31709182, 2019). "RNF8 induces EMT in the breast cancer cells and promotes breast cancer metastasis, suggesting that RNF8 could be used as a potential therapeutic target for the prevention and treatment of breast cancer." (PMID 27259701, 2016). "Although a small study like this cannot exclude the possibility of some other rare mutations in RNF8, UBC13 and MMS2 might predispose to breast cancer, based on our findings they unlikely make any sizeable contribution to cancer predisposition." (PMID 21774837, 2011).
lung carcinoma (7 papers, 2016 to 2023). "RNF8 mediates K63-linked polyubiquitin and stabilization of Slug, promoting Epithelial-Mesenchymal Transition of lung cancer cells." (PMID 36202787, 2022). "As an E3 ligase, RNF8 activates Akt by K63-linked ubiquitination, which facilitates proliferation of lung cancer cells." (PMID 36202787, 2022). "Consistent with our findings in this study, previous studies have revealed that RNF8 promotes EMT in lung cancer cells via stabilization of slug and facilitates cancer chemoresistance and progression by triggering K63-linked ubiquitination of Twist." (PMID 37154586, 2023). "The critical roles of RNF8 in lung cancer tumorigenesis, bladder cancer radiosensitivity, hepatocellular carcinoma growth, and metastasis were also revealed recently." (PMID 35831895, 2022). "In our previous study, we also revealed that RNF8 promoted epithelial–mesenchymal transition in lung cancer." (PMID 35831895, 2022). "RNF8 also promotes tumorigenesis in lung cancer, and silencing RNF8 sensitized bladder cancer to radiotherapy." (PMID 35831895, 2022). "In addition, Xuet al. also reported that RNF8 promotes lung cancer cell survival and resistance to DNA damage by regulating AKT." (PMID 37154586, 2023). "RNF8, an E3 ligase important for the DNA damage response, has been proven to facilitate the progression of breast and lung cancer, but its role in HCC remains unclear." (PMID 37154586, 2023). "Moreover, RNF8 utilizes the RING domain, mediating Lys63-linked Ub chains, which is required for DNA double-strand break (DSB) signaling and the downstream BRCA1 tumor suppressor recruitment or lung cancer cell proliferation." (PMID 35874839, 2022). "Consistent with this idea, RNF8 localizes to the cytoplasm where it interacts with HERC2 and NEURL4 in neurons, IKKα/β, as well as Akt in lung cancer." (PMID 37468549, 2023).
Infertility (4 papers, 2011 to 2025). "Rnf8 deficient males exhibit complete or partial infertility, impaired ubiquitylation of H2A in the XY body, and failure of global nucleosome removal; however, they are proficient in meiotic sex chromosome inactivation." (PMID 21552324, 2011). "In mice, knockout of rnf8 led to a failure in spermiation, suggesting that Rnf8 is required for spermatogenesis and that its absence could result in infertility." (PMID 35886966, 2022). "Mice lacking RNF8 are able to progress through meiosis with no observable chromosomal fusion, although post-meiotic defects result in abnormal spermatids and infertility." (PMID 25934699, 2015).
RIDDLE syndrome (4 papers, 2010 to 2021). A syndrome of increased radiosensitivity, immunodeficiency, mild motor control and learning difficulties, facial dysmorphism, and short stature. "The importance of RNF8 is underscored by the increase in spontaneous tumorigenesis in mice lacking RNF8 and certain human DNA repair deficiency disorders such as the RIDDLE syndrome." (PMID 33933452, 2021). "While no human syndrome/disease have been reported yet to associate with RNF8 mutations, Rnf8-/- mice, similar to the RIDDLE syndrome patient, suffer from defective IgH Class Switch Recombination and are immunodeficient." (PMID 21054854, 2010). "It is of interest that another E3 ligase, RNF168, which acts together with UBC13 to amplify the RNF8-dependent histone ubiquitylation has been shown to be defected in RIDDLE syndrome, which is an immunodeficiency and radiosensitivity disorder." (PMID 21774837, 2011). "Studies of mouse models for Rnf168 mutations are required to determine whether they reproduce characteristics of the RIDDLE syndrome and whether, similar to Rnf8, Rnf168 plays a role in cancer." (PMID 21054854, 2010).
bladder cancer (3 papers, 2016 to 2022). "The deubiquitinating enzyme OTUB1 is known to participate in the classical RNF8 pathway for DNA damage repair and is associated with esophageal cancer, bladder cancer." (PMID 35110531, 2022). "Overall, these results indicated that adenovirus-mediated RNF8 knockdown sensitized bladder cancer cells to radiotherapy in vivo." (PMID 26788910, 2016). "Next, we used an immunofluorescence staining assay to detect endogenous RNF8 expression in bladder cancer cells." (PMID 26788910, 2016). "RNF8 expression was also higher in tissue specimens from bladder cancer patients who underwent radical cystectomy than in normal control bladder cancer-adjacent tissues." (PMID 26788910, 2016). "Altogether, our findings indicated that RNF8 knockdown attenuated radioresistance and enhanced cancer cell death in both in vitro bladder cancer cell lines and in vivo malignant bladder tumor models established in nude mice." (PMID 26788910, 2016). "Collectively, these results indicated that in RNF8-silenced bladder cancer cells, γ-H2AX and MDC1, which function upstream of RNF8, clearly formed IRIF after radiotherapy." (PMID 26788910, 2016). "The results showed that the expression of RNF8 in the three bladder cancer cell lines was upregulated compared to the control urothelial cell line SV-HUC-1." (PMID 26788910, 2016). "Our data showed that RNF8 was highly expressed in bladder cancer cells and that RNF8 accumulated at DSB sites after radiotherapy." (PMID 26788910, 2016). "The results of this analysis showed that in bladder cancer cells, RNF8 participated in the radiotherapy-induced DNA damage response via the ubiquitination of H2A and H2B." (PMID 26788910, 2016). "Altogether, these results suggested that the downregulation of RNF8 sensitized bladder cancer cells to radiotherapy." (PMID 26788910, 2016). "To explore whether RNF8 participated in the DDR in bladder cancer cells, we utilized T24 cells to examine the process of post-irradiation DNA damage repair in the presence or absence of RNF8 knockdown by detecting γ-H2AX foci at different time points." (PMID 26788910, 2016). "Moreover, we found that RNF8 knockdown sensitized bladder cancer cells to radiotherapy, as demonstrated by reduced cell survival." (PMID 26788910, 2016). "Correspondingly, high expression of RNF8 might reduce the efficacy of radiotherapy for bladder cancer." (PMID 26788910, 2016). "We observed that the expression of RNF8 was increased in bladder cancer cells and that this change in RNF8 expression could be reversed by adenovirus-mediated shRNA treatment." (PMID 26788910, 2016). "As RNF8 performs a pivotal function in the response to DSBs, we hypothesized that the upregulation of RNF8 might result in the resistance of bladder cancer to radiotherapy." (PMID 26788910, 2016). "To further investigate the role of RNF8 in DNA damage repair in bladder cancer cells, we depleted RNF8 using shRNA and examined whether the formation of IRIF of various DNA damage signaling/repair proteins was RNF8-dependent." (PMID 26788910, 2016). "Thus, we demonstrated that RNF8 was crucial for IR-induced DNA damage repair in bladder cancer cells." (PMID 26788910, 2016). "Because RNF8 knockdown sensitized bladder cancer cells to radiotherapy in vitro, we further performed in vivo experiments to explore whether this effect of RNF8 could be observed in animal models." (PMID 26788910, 2016). "We observed that RNF8 was highly expressed in bladder cancer cells." (PMID 26788910, 2016). "To investigate whether RNF8 is spontaneously expressed in bladder cancer cells, we first analyzed three urothelial carcinoma cell lines, T24, BIU87 and 5637, as approximately 90% of malignant bladder tumors are urothelial cell carcinomas." (PMID 26788910, 2016). "Altogether, our results indicated that RNF8 might be a novel target for bladder cancer treatment." (PMID 26788910, 2016).
bladder cancer (continued). "Therefore, downregulation of RNF8 resulted in enhanced IR-induced apoptotic cell death, and this finding suggested that combination treatment of bladder cancer cells with shRNF8 and IR can substantially improve the efficacy of radiotherapy by inducing apoptosis." (PMID 26788910, 2016). "Thus, knockdown of RNF8 may suppress bladder cancer cell survival and progression through other supplementary pathways." (PMID 26788910, 2016). "Thus, we hypothesized that RNF8 might be a potential target for bladder cancer treatment." (PMID 26788910, 2016). "The average relative intensity of RNF8 was 1.75-fold higher in the T24, BIU87 and 5637 cells than in the SV-HUC-1 cells and was 2.56-fold higher in the bladder cancer tissues than in the tumor-adjacent control tissues." (PMID 26788910, 2016). "Our results showed that downregulation of RNF8 impaired the recruitment of BRCA1 and RAP80 to DNA damage sites in bladder cancer cells." (PMID 26788910, 2016). "Next, we evaluated 53BP1 IRIF formation in the absence of RNF8 in bladder cancer cells." (PMID 26788910, 2016).
colon cancer (3 papers, 2020 to 2022). "By analyzing the TCGA database and colon cancer tissue microarrays, we found that the expression level of RNF8 was positively correlated with that of c-Myc in colon cancer, which were closely associated with poor survival of colon cancer patients." (PMID 32549753, 2020). "In ubiquitination assay, we observed that overexpression of RNF8 dramatically elevated K63-linked polyubiquitination of β-catenin in colon cancer cells." (PMID 32549753, 2020). "Since our results showed that RNF8 upregulated c-Myc expression by facilitating β-catenin nuclear translocation through K63-linked polyubiquitination, we next examined whether RNF8 affected the proliferation of colon cancer cells." (PMID 32549753, 2020). "This suggested that RNF8 participated in colon cancer progression, which was associated with c-Myc." (PMID 32549753, 2020). "The results showed that, similar to high expression of c-Myc in colon cancer cases, patients with high expression of RNF8 had poor overall survival." (PMID 32549753, 2020). "The results revealed that the enhancing effect of overexpressed RNF8 on c-Myc expression was compromised by silencing β-catenin in colon cancer cells, which was suggested that RNF8 promoted c-Myc expression via β-catenin." (PMID 32549753, 2020). "The relationships of RNF8 and c-Myc staining with clinicopathological features of colon cancer patients are summarized." (PMID 32549753, 2020). "The results showed that RNF8 mRNA level was significantly higher in colon cancer than in normal tissue, which prompted us to explore the role of RNF8 in colon cancer progression." (PMID 32549753, 2020). "To further investigate the role of RNF8 in the proliferation of colon cancer cells in vivo, we subcutaneously injected stable RNF8 knockdown and control HCT116 cells into 4-week-old female nude mice." (PMID 32549753, 2020). "The results showed that the mRNA level of RNF8 was elevated in colon cancer tissues compared with normal controls, as well as that of MYC." (PMID 32549753, 2020). "Next, we performed immunohistochemistry of RNF8 and c-Myc in colon cancer tissue microarrays containing 99 cancer tissues and 78 benign tissues." (PMID 32549753, 2020). "Nevertheless, we observed a significant increase and decrease of β-catenin nuclear translocation when RNF8 was overexpressed and knocked down in colon cancer cells, respectively." (PMID 32549753, 2020). "Our results showed that RNF8 might participate in metabolic reprogramming in colon cancer and clear cell renal cell carcinoma." (PMID 35831895, 2022). "Moreover, the protein level of c-Myc exhibited similar alterations in colon cancer cells with overexpression or knockdown of RNF8." (PMID 32549753, 2020). "In this study, we found a positive correlation between RNF8 and c-Myc in colon cancer tissues." (PMID 32549753, 2020). "Furthermore, overexpressing and knocking down RNF8 increased and decreased the expression of c-Myc in colon cancer cells, respectively." (PMID 32549753, 2020). "In addition, high expression of RNF8 and c-Myc was related to a poor prognosis of colon cancer patients." (PMID 32549753, 2020). "High expression of RNF8 indicated poor survival of colon cancer patients." (PMID 32549753, 2020). "In this study, we detected the transcription level of RNF8 in colon cancer based on the TCGA." (PMID 32549753, 2020). "Furthermore, knockdown of RNF8 significantly inhibited the growth of colon cancer cells in vitro and in vivo." (PMID 32549753, 2020). "To further investigate whether RNF8 was related to the prognosis of colon cancer patients, we performed survival analysis by the Kaplan-Meier curve with the log-rank test in these colon cancer microarray samples." (PMID 32549753, 2020). "Hence, we detected the phosphorylation and protein levels of β-catenin in colon cancer cells with RNF8 overexpression and silencing." (PMID 32549753, 2020).
colon cancer (continued). "Furthermore, the expression of RNF8 was positively correlated with that of c-Myc in colon cancer tissues." (PMID 32549753, 2020). "As a result, we found an interaction between RNF8 and β-catenin in colon cancer cells in vivo." (PMID 32549753, 2020). "We then examined RNF8 and c-Myc protein expression patterns in colon cancer tissue compared with benign tissue by immunohistochemistry and confirmed their positive correlation in colon cancer tissues." (PMID 32549753, 2020). "Therefore, we suspected a function of RNF8 in colon cancer progression." (PMID 32549753, 2020). "Consistent with the TCGA data, the protein levels of RNF8 and MYC gene in colon cancer tissues were both significantly higher than those in benign tissues, as indicated by analysis of the staining scores." (PMID 32549753, 2020). "Thus, we investigated whether RNF8 regulated the proliferation of colon cancer cells." (PMID 32549753, 2020). "To investigate the role of RNF8 in colon cancer, we first analyzed its expression along with that of oncogene MYC, which is frequently dysregulated in colon cancer 26, in 478 colon cancer patients and 41 normal controls based on the TCGA database." (PMID 32549753, 2020). "HCT116 and SW480 cells with stable silencing of RNF8 were performed for the CCK8 proliferation assay and colony formation assay, which demonstrated that silencing RNF8 retarded the growth of colon cancer cells in vitro." (PMID 32549753, 2020). "CCK8 proliferation and colony formation assays showed that silencing RNF8 significantly inhibited the growth of colon cancer cells in vitro, but not that of HEK293 cells." (PMID 32549753, 2020). "We found that RNF8 had a positive relationship with MYC in colon cancer but not in normal tissue." (PMID 32549753, 2020).
glioma (3 papers, 2021 to 2023). A benign or malignant brain and spinal cord tumor that arises from glial cells (astrocytes, oligodendrocytes, ependymal cells). "As RNF8 dysregulation appears to be more strongly linked to a subset of gliomas, we explored The Cancer Genome Atlas (TCGA) reverse phase protein array (RPPA) dataset to identify molecular attributes that are associated with RNF8low tumors." (PMID 37468549, 2023). "In glioma patients, low RNF8 expression is associated with unfavorable patient outcome and RNF8 overexpression suppresses GSC tumorigenicity in an intracranial GBM xenograft model." (PMID 37468549, 2023). "Thus, a subset of gliomas that is associated with high HER2-EGFR signaling preferentially downregulates RNF8 expression as RNF8 overexpression impedes GSC tumorigenicity." (PMID 37468549, 2023). "While a previous study proposed a role of RNF8 in promoting GBM tumorigenicity by mediating histone H3 ubiquitination and degradation, we find that RNF8 mRNA and protein levels are preferentially downregulated in gliomas, particularly those that are associated with high HER2-EGFR signaling." (PMID 37468549, 2023). "That high-grade gliomas (including GBM) tend to avoid high RNF8 expression was further validated at the protein level using glioma microarray (~4-fold less; score +++: 4.3% high-grade vs 16.9% low-grade)." (PMID 37468549, 2023). "Accordingly, RNF8 overexpression impairs glioma stem cell (GSC) mitotic progression in a FHA- and RING-dependent manner." (PMID 37468549, 2023). "Reassuringly, RNF8 expression is also significantly anti-correlated with that of PLK1 in multiple glioma datasets, supporting our CMA hit." (PMID 37468549, 2023). "Consistently, low RNF8 expression portended inferior patient outcome in multiple glioma cohorts." (PMID 37468549, 2023). "Importantly, low RNF8 expression correlates with inferior glioma outcome and RNF8 overexpression impedes GSC tumorigenicity." (PMID 37468549, 2023). "In summary, our work highlights RNF8 downregulation as a strategy exploited by GSC to prevent mitotic checkpoint, and more importantly, a previously unrecognized CAMK2D-RNF8-MAD2 complex that can generate mitotic checkpoint signal in glioma." (PMID 37468549, 2023).
immunodeficiencies (3 papers, 2010 to 2013). "Loss of Rnf8 in mice results in many defects including reduced growth, radiosensitivity, male sterility and immunodeficiency." (PMID 23382699, 2013).